FAP (fibroblast activation protein alpha)
Diseases named in the same sentence as FAP in open-access papers (continued):
Sharing a sentence is not in itself a finding about the gene and the disease.
cancer (continued). "FAP-4-1BBL is a bispecific costimulator targeting the Fibroblast Activation Protein (FAP) expressed in cancer-associated fibroblasts, and the 4-1BB (CD137) receptor, which is expressed in activated T cells." (PMID 39444607, 2024). "Fibroblast activation protein (FAP) overexpression on cancer-associated fibroblasts (CAFs) is associated with poor prognosis and worse clinical outcomes." (PMID 39086477, 2024). "FAP-α is known to be overexpressed mainly by cancer-associated fibroblasts in breast, ovarian, and other cancers, while its expression in normal tissues is low or undetectable." (PMID 39048805, 2024). "The small cohort of primary pulmonary adenocarcinomas used in this study showed a strong expression of FAP by cancer-associated fibroblasts, and occasionally by cancer cells themselves, aligning with expectations based on both veterinary and human literature." (PMID 39188902, 2024). "Fibroblast activation protein (FAP) is overexpressed on cancer-associated fibroblasts and can be targeted by FAP inhibitor (FAPI) PET." (PMID 39477500, 2024). "This potentially renders the utility of FAP as a much broader diagnostic and therapeutic target as it can be applied to many cancer types." (PMID 39335703, 2024). "Fibroblast activation protein (FAP) is overexpressed in cancer-associated fibroblasts (CAFs) in more than 90% of epithelial tumors, including CRC, but its level of expression in normal organs is low." (PMID 39376651, 2024). "The overexpression of FAP in CAFs is associated with poor prognosis in several cancers, making it a critical target for therapeutic intervention." (PMID 39335703, 2024). "Since αSMA seemed to be present but not incorporated within the stress fibers on day 8, we further examined fibroblast activation protein (FAP), which has been widely used for screening for activated fibroblasts and cancer-associated fibroblasts." (PMID 39131910, 2024). "Overall, research data suggest that FAP can be considered an independent poor prognostic factor for multiple cancer types and is associated with reduced overall survival in various malignancies." (PMID 39765634, 2024). "Preliminary studies already assessed its efficacy in various advanced and progressive cancers, as FAPα is expressed by cancer-associated fibroblasts, and promising results were obtained." (PMID 39364020, 2024). "FAP is primarily associated with cancer-associated fibroblasts (CAFs), which have a key role in TME by secreting growth factors and forming a physical barrier." (PMID 38655095, 2024). "Recently, we provided evidence that FAP+ cancer‐associated fibroblasts are present in brain metastases of various origins and showed that these cells are localized in COLI‐rich areas." (PMID 38705944, 2024). "Cancer-associated fibroblasts (CAF) expressed well-known markers including FAP, COL1A1, COL10A1, MMP11, and CTHRC120,21, and other genes such as INHBA, SLC12A8, F2R, and COL12A1 in various organs." (PMID 38744958, 2024). "In recent years, fibroblast activating protein (FAP), a biomarker overexpressed by cancer-associated fibroblasts, has emerged as one of the most promising biomarkers in oncology." (PMID 38695960, 2024). "Many cancer-associated fibroblasts differ from normal fibroblasts due to their relatively specific expression of fibroblast activation protein (FAP) inhibitors." (PMID 39201021, 2024). "Fibroblast activation protein (FAP) is a surface‐expressed proteolytic enzyme that is well known for its expression in cancer‐associated fibroblasts." (PMID 38975278, 2024). "FAP is highly expressed by cancer‐associated fibroblasts (CAFs) and is used as a universal marker for these cells." (PMID 39618102, 2024).
cancer (continued). "Fibroblast activation protein (FAP), a type II transmembrane serine protease, is highly expressed in cancer-associated fibroblasts (CAFs)." (PMID 39770488, 2024). "Specifically, in pancreatic (PDAC) and colorectal (CRC) cancers, high FAP levels were linked to more endothelial cells and fibroblasts." (PMID 39035007, 2024). "The positive correlations of VDR expression with the expression of FAP (cancer-associated fibroblast marker), CD68 (macrophage marker), or CD15 (neutrophil marker) were experimentally verified in PTC tissues." (PMID 38639057, 2024). "The present study analyzed the pan-cancer expression; and clinical and mutational profiles of the FAP coding gene." (PMID 39579201, 2024). "Fibroblast activation protein (FAP), a type II transmembrane serine protease of the prolyl oligopeptidase family, is commonly expressed in cancer-associated fibroblasts (CAFs)." (PMID 36864362, 2023). "FAP was upregulated in various types of cancers, including NSCLC, and showed a strong association with the cluster of fibroblasts." (PMID 35951090, 2023). "α-SMA, a marker of cancer associated fibroblasts (CAFs), increased, and FAP-α, a marker of a subset of CAFs associated with immune suppression, decreased with VEGF overexpression." (PMID 37389973, 2023). "As a membrane anchored peptidase highly expressed in cancer-associated fibroblasts (CAFs) in more than 90% of epithelial tumors, fibroblast activating protein (FAP) can lead to the progression of different cancers." (PMID 36675506, 2023). "Fibroblast activation protein (FAP) is regarded as a promising target for the diagnosis and treatment of tumors as it was overexpressed in cancer-associated fibroblasts." (PMID 37057133, 2023). "We found that FAP was exclusively expressed in fibroblasts as well as cancer associated fibroblasts (CAFs) in LIHC (GSE125449)." (PMID 37325617, 2023). "We next analyzed additional markers such as FAPα, associated with CAFs (cancer-associated fibroblasts), and immune cell markers CD163, CD8 and PD-L1." (PMID 37596623, 2023). "The IAFs in a previous UC study expressed FAP, a marker of cancer-associated fibroblasts, and vimentin (VIM) as a marker validated experimentally in IAFs." (PMID 37834250, 2023). "FAP is overexpressed on the cell surface of cancer-associated fibroblasts (CAFs), a type of continuously activated fibroblasts." (PMID 37110717, 2023). "With such striking results, our FAP targeting UniCAR platform has the potential to be used alone or combined with other approaches for cancer therapy and diagnostic imaging, representing an attractive theranostic targeting strategy." (PMID 38102692, 2023). "In over 90% of epithelial tumours, FAP expression is found on the cancer-associated fibroblasts (CAFs)." (PMID 37408254, 2023). "The FAP is known to be overexpressed by cancer-associated fibroblasts and thus upregulated in many neoplastic conditions." (PMID 36769616, 2023). "Fibroblast activation protein alpha (FAP) is highly expressed by cancer-associated fibroblasts in multiple epithelial cancers." (PMID 37333052, 2023). "Comparison of FAP gene expression between the N and T groups identified unique functions enriched in DEGs, indicating differences in FAPs between normal breast and cancer associated adipose, and showed 307 GEGs of which top 25 are shown in a heatmap." (PMID 37153595, 2023). "α‐Smooth muscle actin (αSMA) and fibroblast activation protein (FAP), markers of cancer‐associated fibroblasts (CAFs), were detected in all MSCs." (PMID 37693056, 2023). "A study in cancer-associated fibroblasts confirmed that FAP suppresses immune cell response by enhancing MDSC recruitment by promoting the STAT3 C-C motif chemokine ligand 2 signaling." (PMID 37006278, 2023). "More recently, there are also many expectations regarding fibroblast activation protein (FAP), a molecule overexpressed in the stroma of a variety of cancers, considered a promising target structure for diagnostic and therapeutic approaches." (PMID 37629397, 2023).
cancer (continued). "Other developments include targeting fibroblast activation protein (FAP), an essential protease of cancer-associated fibroblasts (CAFs) that is highly overexpressed in many cancers, including lung, pancreatic, ovarian, and colorectal tumors." (PMID 36853475, 2023). "Many tumors contain cancer-associated fibroblasts (CAFs), which express high levels of fibroblast activation protein (FAP)." (PMID 37583569, 2023). "The fibroblast activation protein (FAP) is highly expressed on cancer-associated fibroblasts in many tumors." (PMID 36765866, 2023). "FAP has been identified as an independent biomarker associated with a poor prognosis in a growing number of cancers." (PMID 37864148, 2023). "The data obtained for cancer-associated fibroblasts (CAFs) suggest that FAPα-positive fibroblasts have a specific secretory profile." (PMID 38136590, 2023). "Fibroblast activation protein (FAP) is higher expressed on cancer-associated fibroblasts (CAFs) in most malignant epithelial neoplasms, which is lower expressed in normal tissues." (PMID 36879039, 2023). "Regarding cancer-associated fibroblasts (CAFs), membrane-bound FAP expression contributes to immune evasion and chemoresistance and appears to be crucial for invasiveness and metastasis." (PMID 36672341, 2023). "We find that FAP is up-regulated in most cancer types, and increased FAP expression is associated with advanced pathological stages or poor prognosis in several cancers." (PMID 37166418, 2023). "FAP is one of the surface markers expressed by cancer-associated fibroblasts (CAFs), which are part of the stroma in various malignant tumors." (PMID 35997853, 2023). "Although the number of similar studies related to RA is currently low, studies of FAP in other disease areas, especially studies on cancer-associated fibroblasts, can provide a reference." (PMID 37006278, 2023). "Higher expression of FAP is associated with advanced pathological stages in cancers including BLCA, COAD, ESCA, KIRP, OV, STAD, TGCT and THCA." (PMID 37166418, 2023). "FAP levels are inversely associated with all-cause mortality in the Framingham Heart Study, Malmö Diet and Cancer Study, and Jackson Heart Study." (PMID 37036009, 2023). "To define mechanisms involved, here we treat established desmoplastic pancreatic tumors with CAR T cells directed to fibroblast activation protein (FAP), an enzyme highly overexpressed on a subset of cancer-associated fibroblasts (CAFs)." (PMID 37607999, 2023). "FAP is a cell surface serine protease expressed by reactive fibroblast especially cancer associated fibroblast." (PMID 37035187, 2023). "We evaluated the immunohistochemical expression of HHLA2 and fibroblast activation protein (FAP), which is a marker of cancer-associated fibroblasts, in UTUC tissues from 85 patients who underwent nephroureterectomy." (PMID 36598731, 2023). "We labeled cell types as endothelial cell (Endothelial, gene expression of PLVAP, KDR, PTPRB) and cancer associated fibroblasts cell (CAFs, gene expression of FAP, MMP11, PDGFRB, SFRP2, PDGFRA, ADAMTS2)." (PMID 37065499, 2023). "The ever-evolving search for cellular targets led to the discovery of fibroblast activation protein (FAP), a transmembrane glycoprotein expressed on activated fibroblasts such as cancer-associated fibroblasts (CAFs)." (PMID 37370912, 2023). "The Fibroblast Activation Protein Inhibitor (FAPI) PET detects the fibroblast activation protein (FAP), which is overexpressed by cancer-associated fibroblasts (CAFs) in the cancer microenvironment." (PMID 38201625, 2023). "The expression of FAP was also found to be associated with poor prognosis in a variety of malignant tumors, such as ovarian cancer, pancreatic cancer, colon cancer, and hepatocellular carcinoma." (PMID 37057133, 2023). "The vector with the FAP-BiTE transgene was cytotoxic for both cancer cells and cancer-associated fibroblasts (CAF) in the presence of T cells after infecting the ovarian cancer cells (SCOV-3)." (PMID 37046608, 2023).
cancer (continued). "FAP is selectively expressed at high levels by cancer-associated fibroblasts in more than 90% of human epithelial cancers." (PMID 37024301, 2023). "The tumor microenvironment (TME) around cancer cells, particularly the presence of cancer-associated fibroblasts (CAFs) expressing fibroblast activation protein (FAP), plays a critical role in cancer progression." (PMID 38030859, 2023). "The overexpression of fibroblast activation protein alpha (FAPα) is a characteristic of cancer-associated fibroblasts (CAFs), which are located in the stroma of epithelial cells." (PMID 38140090, 2023). "Depletion of FAP-expressing cells in lung and pancreatic carcinomas in mouse tumors causes rapid hypoxic necrosis of cancer and stromal cells in these immunogenic tumors, mediated by interferon-γ and TNFα." (PMID 37046676, 2023). "Prior studies suggest that polarization of macrophages toward an SPP1+ state is a result of TME properties, including oxygen tension, the presence of FAP+ cancer-associated fibroblasts, and ECM composition, consistent with our pathway analysis." (PMID 38036590, 2023). "Both types of transition are sources of cancer-associated fibroblasts, which typically express high levels of FAP." (PMID 36574660, 2023). "This dynamic relationship between cancer and FAP has substantial diagnostic and therapeutic implications." (PMID 37892020, 2023). "FAP-α-positive cancer associated fibroblasts (CAFs) have been found to induce immunosuppression via STAT3-CCL2 signaling, and by promoting immune checkpoint blockade resistance." (PMID 36937451, 2023). "Targeting cancer-associated fibroblasts (CAFs) to treat cancer was initially evaluated with inhibitors of fibroblast-activation protein (FAP), a type-II transmembrane serine protease highly expressed by fibroblasts." (PMID 37771596, 2023). "Fibroblast activation protein (FAP), a type II transmembrane glycoprotein, is overexpressed in cancer-associated fibroblasts but expressed at low levels in normal fibroblasts." (PMID 37321827, 2023). "Various factors, including genetic and epigenetic alterations, TME, and signaling pathways implicated in cancer progression, can influence the expression of FAP, providing a potential explanation for this phenomenon." (PMID 37490719, 2023). "Meanwhile, several cancer-associated studies have shown that high expression of FAP promotes cell cycle progression, while FAP silencing is accompanied by cell cycle silencing." (PMID 37006278, 2023). "Hormones such as progesterone and estradiol were predicted to be associated with FAP overexpression within our pan-cancer cohort—with both compounds being known regulators of angiogenesis." (PMID 36672341, 2023). "As expected, FAP showed strongly positive association with cancer-associated fibroblasts (CAFs), in line with that FAP is a universal marker of CAFs and abundantly express among CAFs." (PMID 37166418, 2023). "Since CAFs have significant roles in cancer tissue such as involving in the immune system modulation, FAP-expressing CAFs were recently associated with immunosuppression and resistance to immunotherapies, confirmed in preclinical studies." (PMID 37608378, 2023). "Cancer-associated fibroblasts (CAFs) within the TME are identified by biomarkers such as fibroblast activation protein alpha (FAPα), which are expressed on their surfaces." (PMID 38140090, 2023). "This, coupled with the cancer supportive role of CAFs, makes FAP a promising diagnostic and therapeutic target." (PMID 37333052, 2023). "FAP’s restricted tissue distribution pattern makes it a highly promising cancer diagnostic marker and therapeutic target." (PMID 37110717, 2023). "Fibroblast activation protein‐α (FAP) is a membrane‐bound serine protease and is specifically expressed on the surface of reactive cancer‐associated fibroblasts (CAFs) that constitute a major stromal component of most solid tumors." (PMID 37773704, 2023).
cancer (continued). "While FAP has been recognized as a potential diagnostic or therapeutic cancer target for decades, the surge of radiolabeled FAP-targeting molecules has the potential to revolutionize its perspective." (PMID 36813980, 2023). "Fibroblast activation protein alpha (FAP) is a dual‐specificity serine protease that is strongly associated with the development and progression of human carcinomas." (PMID 36382346, 2023). "Recent studies using syngeneic carcinoma models indicate that CAFs expressing FAP are responsible for immune-evasion associated with a pro-tumourigenic TME." (PMID 37516803, 2023). "FAP is overexpressed in the cancer-associated fibroblasts (CAFs) of 90% of all epithelial carcinomas, including HCC." (PMID 37899452, 2023). "It is characterized by a strong desmoplastic response, and the association between FAP overexpression and a poor cancer prognosis has led to development of FAP-specific inhibitors (FAPIs)." (PMID 36464732, 2022). "In a mouse lung carcinoma model, depletion of FAP-expressing stromal cells causes acute cytokine-induced hypoxic death of both cancer and stromal cells." (PMID 35884382, 2022). "Fibroblast activation protein (FAP)-targeted NIR-PIT provides selective depletion of cancer-associated fibroblasts, which promote cancer growth and facilitate drug resistance." (PMID 35740662, 2022). "In our study, we firstly demonstrated the aberrant overexpression of Nectin4 on both primary and metastatic solid tumors and FAP on cancer-associated fibroblasts." (PMID 36479116, 2022). "In our study, more advanced stage and vascular invasion were associated with high expression of FAP in cancer cells." (PMID 35818720, 2022). "The TIMER database was utilized to investigate the association between COL8A1, COL10A1, CTHRC1, and FAP, and immune cell infiltration, as immune cell levels correlate with the proliferation and progression of cancer cells." (PMID 35910202, 2022). "Fibroblast activation protein (FAP) is overexpressed by cancer-associated fibroblasts (CAFs) in several cancer types." (PMID 35328267, 2022). "Fibroblast activation protein-alpha (FAP) was abundantly and stably expressed in cancer-associated fibroblasts (CAFs) in the cancer stroma." (PMID 35359436, 2022). "Previous studies have shown that fibroblast activation protein (FAP) is overexpressed in the cancer-associated fibroblasts (CAFs) of gastric cancer and plays an important role in the invasion and migration of gastric carcinomas." (PMID 35471681, 2022). "Recently, the Fisher group engineered another BiTE armed oncolytic adenovirus (EnAd-FAP-BiTE), which is targeted fibroblast activation protein (FAP) in cancer-associated fibroblasts (CAFs)." (PMID 35756634, 2022). "The authors found that FAPi-PET was positive in more than 50% of cases from 11 cancer types, with variability in the intensity of FAP expression strongly associated with FAP expression assessed by immunohistochemistry in the surgery specimen." (PMID 35327325, 2022). "High FAP expression is restricted almost exclusively to cancer-associated fibroblasts and serves as an independent negative prognostic factor for multiple types of cancer." (PMID 34740953, 2022). "FAPI-PET was introduced as a new imaging method for tumors targeting FAP-positive cancer-associated fibroblasts, which are present in a large variety of cancers." (PMID 36358720, 2022). "Both Endo_1 and Fib_1 expressed fibroblast activation protein (FAP), a classical cancer-associated fibroblast (CAF) marker." (PMID 35999201, 2022). "FAP, which was discovered more than 30 y ago, is overexpressed on the cancer-associated fibroblasts of over 90% of epithelial tumors such as breast, colorectal, lung, ovarian, and pancreatic adenocarcinomas." (PMID 34168013, 2022).